MORC2 (MORC family CW-type zinc finger 2)
Diseases named in the same sentence as MORC2 in open-access papers (continued):
Sharing a sentence is not in itself a finding about the gene and the disease.
neuropathies (7 papers, 2018 to 2025). "Considering that mutation in the ATPase module of MORC2 causes neurodevelopmental disorder, the high similarity of the ATPase domain is necessary to develop neuropathy in mice." (PMID 34695197, 2021). "All identified mutations associated with MORC2-related neuropathies are localized in the N-terminal ATPase module." (PMID 34059105, 2021). "Because the MORC2 p.S87L missense mutation leads to severe neuropathy in humans, we selected p.S87L as a target mutation in the design of our mouse model." (PMID 34695197, 2021). "Our study confirmed that MORC2-related neuropathies exist in the Chinese population at a relatively high mutation rate." (PMID 34059105, 2021). "Mutations in MORC2 are associated with neuropathies and these disease mutations have been found to affect MORC2 structure and HUSH function." (PMID 33144593, 2020). "It should be noted, however, that MORC2-associated neuropathies are subject to autosomal dominant inheritance." (PMID 29440755, 2018). "These defects lead to the modulation of HUSH function, thus providing a molecular basis for understanding MORC2-associated neuropathies." (PMID 29440755, 2018). "MORC2 is the only gene in the MORC family in which mutations have been reported to cause neuropathies in humans." (PMID 29440755, 2018). "Here we have described a molecular basis for understanding the MORC2 effector function in human epigenetic silencing and the varied mechanisms of misregulation that underlie MORC2-associated neuropathies." (PMID 29440755, 2018). "Exome sequencing data from patients with genetically unsolved neuropathies have recently reported missense mutations in the ATPase module of the MORC2 gene." (PMID 29440755, 2018). "Our MORC2 structures span residues 1–551, including all reported sites of neuropathy-causing mutations." (PMID 29440755, 2018). "Two MORC2 mutations, S87L and T424R, have been reported to cause congenital or infantile onset of neuropathies, distinct from the later onset that was reported for patients bearing the R252W (or other) mutations." (PMID 29440755, 2018). "Having isolated a MORC2 construct competent for nucleotide binding and hydrolysis, we sought to generate mechanistic insights into the biochemical properties of MORC2 and the molecular basis of MORC2-associated neuropathies via structural analysis." (PMID 29440755, 2018). "We would, therefore, predict that there are other MORC2 mutations associated with undiagnosed neuropathies." (PMID 29440755, 2018). "We propose distinct structural mechanisms that explain how these functions of MORC2 are misregulated in neuropathy-associated variants: destabilization of the ATPase-CW module, trapping the ATP lid, or perturbing the dimer interface." (PMID 29440755, 2018). "However, MORC2-related neuropathies seem more complex since the same mutation, such as p.Y394C, can generate different outcomes in patients." (PMID 35722617, 2022). "Interestingly, all MORC2 mutations causing neuropathies are localized in its ATPase catalytic domain and consequently are likely to impact MORC2 ATPase activity, which is essential for its functions." (PMID 35722617, 2022). "All identified mutations associated with MORC2-related neuropathies are localized in the N-terminal ATPase module, which might be critical to MORC2 protein function." (PMID 34059105, 2021). "The etiology of MORC2 mutation-mediated neuropathy remains uncertain." (PMID 34695197, 2021). "Since both gain and loss of MORC2 molecular function are linked to neuropathies, there are, in theory, a large number of MORC2 mutations that could cause disease including those that compromise the stability of the ATPase module." (PMID 29440755, 2018). "We next tested whether MORC2 mutations reported to cause neuropathies affected the ATPase activity of MORC2." (PMID 29440755, 2018).
neuropathies (continued). "However, some studies have suggested that neuronal and muscular pathologies may occur independently in neuropathies associated with MORC2 variants." (PMID 40760337, 2025). "A loss of FAS causes microcephaly and is associated with developmental epileptic encephalopathy, two phenotypes also observed in some patients with MORC2-related neuropathies." (PMID 35722617, 2022). "We also reviewed the literature to further refine the clinical spectrum of MORC2-related neuropathies, to investigate the relationship between the genotype and the phenotype." (PMID 34059105, 2021). "Furthermore, as a hydrophobic molecule, estrogen can cross the blood–brain barrier and reach the spinal cord and peripheral nerves through the bloodstream, making it advantageous for preventing MORC2 haploinsufficiency-mediated neuropathy." (PMID 40760337, 2025). "Therefore, further investigations supported by next-generation sequencing technologies will certainly improve the understanding of the pathophysiology of MORC2-related neuropathies." (PMID 35722617, 2022). "Our findings expand the ethnic, phenotypic, and genetic diversity of MORC2-related neuropathies." (PMID 34059105, 2021). "Thus, MORC2 missense mutation might need to be categorized as new neuropathy rather than solely CMT2Z." (PMID 34695197, 2021).
Ataxia (6 papers, 2021 to 2023). Ataxia refers to impaired coordination of voluntary muscle movement. "There are clinical reports of cerebellar ataxia and craniofacial disorder in human patients with MORC2 gene mutation." (PMID 34695197, 2021). "Rare cases of LS could be caused by genes not directly involved in OXPHOS function—MORC2-associated SMA-like phenotypes and VPS13D-associated ataxia + phenotypes are a bright illustration of LS phenocopy." (PMID 36675121, 2023).
hepatocellular carcinoma (6 papers, 2019 to 2024). A malignant tumor that arises from hepatocytes. "MORC2 promotes the stemness and tumorigenesis by facilitating DNA methylation-dependent silencing of Hippo signaling in hepatocellular carcinoma cells." (PMID 32612672, 2020). "Moreover, MORC2 promotes cancer stemness and tumorigenesis by facilitating DNA-methylation-dependent silencing of Hippo signaling in hepatocellular carcinoma." (PMID 36234785, 2022). "Additionally, MORC2 is essential for maintaining cancer stemness, sorafenib resistance and tumorigenesis of hepatocellular carcinoma (HCC) by repressing two critical components involved in the Hippo signaling pathway, NF2 and KIBRA, at the transcriptional level." (PMID 31180332, 2019).
cholangiocarcinoma (5 papers, 2019 to 2024). A carcinoma that arises from the intrahepatic biliary tree (intrahepatic cholangiocarcinoma) or from the junction, or adjacent to the junction, of the right and left hepatic ducts (hilar cholangiocarcinoma). "MORC2 has been shown to promote metastasis of triple-negative breast cancer and cholangiocarcinoma by regulating the EMT process." (PMID 39048555, 2024). "Studies have shown that MORC2 promotes cell growth and metastasis in human cholangiocarcinoma and is negatively regulated by miR-186-5p, the MORC2-mutant M276I promotes metastasis of triple-negative breast cancer by regulating CD44 splicing." (PMID 36234785, 2022). "Similarly, overexpression of MORC2 promoted cholangiocarcinoma cell metastasis through epithelial–mesenchymal transition (EMT) and cell proliferation through serine/threonine kinase (AKT) signaling." (PMID 37692502, 2024). "miR-186-5p expression was down-regulated in CRC, and low expression of miR-186-5p leads to the overexpression of MORC2, which promotes the growth and metastasis of cholangiocarcinoma (CCA) cells by regulating Akt signaling and EMT." (PMID 37692502, 2024).
colorectal cancer (5 papers, 2022 to 2025). A primary or metastatic malignant neoplasm that affects the colon or rectum. "Intriguingly, reconstituting endogenously PGK1- or MORC2-depleted HT29 colorectal cancer cells with the phosphorylation-defective mutants PGK1-S256A or MORC2-S711A, respectively, conferred heightened radiosensitivity relative to WT counterparts." (PMID 41213904, 2025). "To further investigate the mechanism of MORC2 in the development of colorectal cancer, we used immunoprecipitation combined with mass spectrometry to identify proteins that interacted with MORC2." (PMID 39048555, 2024). "MORC2 is found to be up-regulated in multiple cancers, including breast cancer, gastric cancer, colorectal cancer and liver cancer." (PMID 39048555, 2024). "In summary, our results reveal a novel mechanism by which MORC2 promotes colorectal cancer development by promoting the isoform switch of CDK5RAP2 L to CDK5RAP2 S through interacting with RBM39." (PMID 39048555, 2024). "Our findings not only provide a novel mechanism but also suggest a treatment strategy of targeting the MORC2/RBM39/CDK5RAP2 axis for colorectal cancer therapy." (PMID 39048555, 2024). "In colorectal cancer, MORC2 binds to RBM39 to promote alternative splicing of pre-CDK5RAP2, converting CDK5RAP2 L into a variant CDK5RAP2 S. CDK5RAP2 S promotes invasion and metastasis of colon cancer cells in vitro and in vivo." (PMID 39048555, 2024). "MORC2 is overexpressed in colorectal cancer, and by controlling cellular senescence, it promotes tumorigenesis." (PMID 37892209, 2023). "Recently, it has been shown that MORC2 promotes the development of an aggressive colorectal cancer phenotype through inhibition of NDRG1." (PMID 36234785, 2022). "Importantly, high protein levels of MORC2, RBM39 and Slug are strongly associated with metastasis and poor clinical outcomes of colorectal cancer patients." (PMID 39048555, 2024). "Correlation analysis revealed that MORC2 and RBM39, MORC2 and Slug, RBM39 and Slug expression were positively correlated in colorectal cancer with metastasis." (PMID 39048555, 2024). "Here, our results indicate that CDK5RAP2 S regulated by MORC2 and RBM39 promotes colorectal cancer progression." (PMID 39048555, 2024). "We ranked splicing factors that bind to MORC2 and selected RBM39, an RNA-binding protein that promoted the survival of colorectal cancer cells by regulating the splicing of various genes." (PMID 39048555, 2024). "We found both RNA and protein expression levels of MORC2 and RBM39 were significantly higher in colorectal cancer tissues in our cohort." (PMID 39048555, 2024). "Next, we analyzed the expression of MORC2 and RBM39 in patients with colorectal cancer." (PMID 39048555, 2024). "Taken together, our findings uncover a novel mechanism by which MORC2 promotes colorectal cancer metastasis, through RBM39-mediated pre-CDK5RAP2 alternative splicing and highlight the MORC2/RBM39/CDK5RAP2 axis as a potential therapeutic target for colorectal cancer." (PMID 39048555, 2024). "The results demonstrated that MORC2, RBM39, and Slug were highly expressed in colorectal cancer tissues with metastasis, while E-cadherin was not or lowly expressed." (PMID 39048555, 2024). "MeRIP-seq and RNA-sequencing revealed four genes, WD- repeat domain 72 (WDR72), spectrin beta, non-erythrocytic 2 (SPTBN2), microrchidia 2 (MORC2), and prostate androgen-regulated mucin-like protein 1 (PARM1), which could predict the prognosis of patients with colorectal cancers." (PMID 36835633, 2023).
developmental delay (5 papers, 2021 to 2024). "Besides the p.S87L mutation, patients with similar SMA-like picture were rapidly identified in two unrelated families with a de novo p.T424R (c.1271C > G) MORC2 mutation associated with cerebellar atrophy, diaphragmatic paralysis, developmental delay." (PMID 35722617, 2022).
liver cancer (4 papers, 2021 to 2025). An epithelial or non-epithelial malignant neoplasm that arises from the liver. "The proliferation and clonogenicity of liver cancer cells, as well as their migratory and invasive abilities, could be inhibited by knocking down MORC2." (PMID 34839357, 2021). "However, the precise mechanism of dysregulation of MORC2 in liver cancer is still unclear." (PMID 34839357, 2021).
breast tumor (3 papers, 2022 to 2023). "We also propose a promising strategy to sensitize MORC2-driven breast tumors to chemotherapeutic drugs by inhibition of the SUMO pathway." (PMID 36793866, 2023). "For this reason, MORC2 SUMOylation is critical in breast tumor resistance to DNA-damaging chemotherapy." (PMID 36793866, 2023). "To determine the clinical relevance of our findings, we performed immunohistochemical (IHC) staining using a tissue microarray (TMA) containing 126 human breast tumor samples with an antibody against MORC2, O-GlcNAc, OGT, GFAT, SNAIL, or CTGF." (PMID 34974534, 2022). "Clinically, high expression of OGT, MORC2, SNAIL, and CTGF in breast tumors is associated with poor patient prognosis." (PMID 34974534, 2022). "Therefore, SUMO modification-deficient MORC2 results in more severe DNA damage and renders breast tumors more sensitive to ADR than WT MORC2." (PMID 36793866, 2023). "In summary, findings presented here suggest that HSP90 N‐terminal inhibitors induce autophagic degradation of MORC2 in a HSP90‐independent manner through disrupting its homodimerization and are effective against MORC2‐expressing breast tumours irrespective of HSP90 expression status." (PMID 35522895, 2022).
colon adenocarcinoma (3 papers, 2022 to 2025). "GEPIA database analysis showed high MORC2 and RBM39 mRNA expression in colon adenocarcinoma tissues." (PMID 39048555, 2024). "Results showed increased expression of ENO3, MORC2, SUCLG2 and ELOVL6, and decreased expression of CPT2 in all examined colon adenocarcinoma cell lines." (PMID 36568396, 2022). "Moreover, qRT-PCR revealed upregulated expression of ENO3, MORC2, SUCLG2 and ELOVL6, and downregulated expression of CPT2 in all examined colon adenocarcinoma cell lines." (PMID 36568396, 2022).
lung carcinoma (3 papers, 2021 to 2022). "MORC2 could activate the Wnt/β-catenin signaling pathway and stimulate the recruitment of tumor-associated macrophages, contributing to the promotion of lung tumor growth and metastasis in a series of lung cancer cell lines, including A549, PC-9, H1299, NCI-H2170, NCI-H226, and LL/2 cells." (PMID 34839357, 2021). "MORC family CW-type zinc finger 2 (MORC2) promotes cancer progression by enhancing angiogenesis and recruitment of tumor-associated macrophage via the Wnt/β-catenin pathway in lung cancer." (PMID 34281588, 2021). "Furthermore, MORC2 increases the level of aldehyde dehydrogenase-1 protein in lung cancer, which is regarded as a feature of cancer stem cells." (PMID 34839357, 2021).
Sensory neuropathy (3 papers, 2021 to 2022). Peripheral neuropathy affecting the sensory nerves. "Mutations in MORC2 were first reported in 2016 in association with a progressive axonal and sensory neuropathy frequently presenting in the first decade of life." (PMID 35328054, 2022). "Recent studies on MORC2 mutations show a remarkable heterogeneity in clinical features and disease severity, ranging from axonal motor and sensory neuropathy to a complex multisystem disorder." (PMID 34059105, 2021).
triple-negative breast carcinoma (3 papers, 2022 to 2024). An invasive breast carcinoma which is negative for expression of estrogen receptor (ER), progesterone receptor (PR), and human epidermal growth factor receptor 2 (HER2). "Recently, Microrchidia 2 (MORC2) has been documented as a prognostic and predictive biomarker in triple negative breast cancer (TNBC)." (PMID 37352040, 2023). "However, only one study found that MORC2 mutant M276I regulated hnRNPM-mediated CD44 splicing switch to promote invasion and metastasis in triple-negative breast cancer cells." (PMID 39048555, 2024).
Cerebellar atrophy (2 papers, 2021). Cerebellar atrophy is defined as a cerebellum with initially normal structures, in a posterior fossa with normal size, which displays enlarged fissures (interfolial spaces) in comparison to the foliae secondary to loss of tissue. "Patients with CMT2Z with MORC2 p.T362R mutation develop cerebellar atrophy." (PMID 34695197, 2021).
colon cancer (2 papers, 2024 to 2025). "Some studies showed that upregulated MORC2 is predictive of a worse prognosis of colon cancer." (PMID 39812044, 2025). "Importantly, MORC2 was positively correlated with RBM39 expression in colon cancer." (PMID 39048555, 2024). "Taken together, MORC2 and RBM39 promote EMT, migration and invasion of colon cancer cells via CDK5RAP2 S." (PMID 39048555, 2024). "Here, we identified a novel target gene CDK5RAP2, whose alternative splicing was regulated by RBM39 and MORC2, contributing to a better understanding of the mechanisms of RBM39 and MORC2 in colon cancer." (PMID 39048555, 2024). "Taken together, these data indicate the direct interaction between MORC2 and RBM39 in the nucleus of colon cancer cells." (PMID 39048555, 2024). "In this study, our data demonstrate the functional links between MORC2, RBM39 and the downstream CDK5RAP2 whose alternative splicing they regulate in EMT and metastasis of colon cancer cells." (PMID 39048555, 2024). "Then we verified that MORC2 and RBM39 promoted EMT in colon cancer cells." (PMID 39048555, 2024). "However, the effect and mechanism of MORC2 on alternative splicing in colon cancer are not understood." (PMID 39048555, 2024). "However, whether MORC2 regulates RBM39-mediated alternative splicing in colon cancer is not known." (PMID 39048555, 2024).
gastric tumor (2 papers, 2015 to 2019). "The down-regulation of C/EBPα and up-regulation of MORC2 accounted for ~80% in 40 cases of gastric tumor patients." (PMID 30644437, 2019). "Western blot showed that MORC2 was high expression in 58% (40 of 68) of gastric tumor samples, of which p21 was down-regulated in 50% (20 of 40)." (PMID 26098774, 2015). "Furthermore, MORC2 expression correlated negatively with p21 expression in gastric tumors in patients." (PMID 26098774, 2015).
glioma (2 papers, 2022 to 2024). A benign or malignant brain and spinal cord tumor that arises from glial cells (astrocytes, oligodendrocytes, ependymal cells). "In addition, up-regulated MORC2 promotes glioma cell growth by suppressing the NDRG1 promoter activity and regulating PTEN/PI3K/AKT signaling." (PMID 37692502, 2024). "Besides, MORC2 is up-regulated in glioma cells and binds to the NDRG1 promoter to promote glioma cell growth and metastasis by regulating PTEN/PI3K/AKT signaling." (PMID 37692502, 2024). "The study of the microrchidia family CW-type zinc finger 2 (MORC2), which was a chromatin modifier, reported that MORC2 binding to the NDRG1 promotor inactivated PTEN/PI3K/AKT signaling and promoted the growth of glioma cells." (PMID 35448004, 2022).
Infertility (2 papers, 2024 to 2025). "This discrepancy may be attributed to physiological or social infertility that naturally blocks the propagation of severely symptomatic MORC2 mutations to subsequent generations." (PMID 39464795, 2024). "Finally, MORC2 has been identified as an oncogene and deletion in mouse models results in infertility." (PMID 38996041, 2025).
endometrium cancers (1 paper, 2021). "The expression of MORC2 protein is upregulated, and MORC2 exerts its oncogenic activities in multiple cancers, including lung, prostate, liver, brain, breast, stomach, colon, pancreatic, ovarian, and endometrium cancers." (PMID 34839357, 2021).